LEP (leptin)
Diseases named in the same sentence as LEP in open-access papers (continued):
Sharing a sentence is not in itself a finding about the gene and the disease.
diabetes (continued). "Leptin therapy has been found to effectively reverse hyperglycemia and prevent mortality in mouse models of diabetes." (PMID 34446063, 2021). "Several studies have shown that leptin and adiponectin have opposing effects, supporting their use as a ratio, as reported in diabetes, coronary artery disease, and anorexia nervosa." (PMID 33816531, 2021). "We aimed to explore the role and possible mechanism of leptin in lower-extremity artery calcification in patients with type 2 diabetes mellitus (T2DM)." (PMID 34093426, 2021). "In contrast, in a cohort study on 38 obese patients (mean BMI = 47.3 kg/m2) with diabetes who underwent bariatric surgery, those with higher than mean preoperative leptin levels (27.3 ng/mL) had higher glucose levels at 3 months post operation." (PMID 34501456, 2021). "Diabetes also provokes liver fibrogenesis by elevating the production of leptin and TNF-α, which activates the inflammatory pathways that cause hepatic damage and fibrosis." (PMID 33799865, 2021). "Data emerging from research on leptin in diabetes suggest that it is an inflammatory mediator that sustains multifactorial diseases." (PMID 34446063, 2021). "Briefly, long-term increases in the plasmatic levels of leptin or insulin, resulted in insulin or leptin resistance, paving the way to diabetes or fat accumulation." (PMID 33574566, 2021). "Linear regression was performed with leptin, age, waist circumference, hypertension, and diabetes as independent variables predicting cFT/T." (PMID 33179018, 2020). "In particular, accelerated gastric emptying is often observed in early diabetic patients and rodent models of diabetes and genetic knockdown models (Ghrelin, Leptin null models)." (PMID 32635208, 2020). "Therefore, leptin could be a novel approach for protection against the infections in human population susceptible under certain pathological conditions such as malnutrition, diabetes mellitus or HIV infection." (PMID 32824322, 2020). "An increase in leptin mRNA and protein has also been reported following the crocin supplementation in animal models of diabetes mellitus." (PMID 32670418, 2020). "As we sought a diabetes model with at least normal leptin levels, we examined a system in which a high-fat diet regime in mice at thermoneutrality preceded the streptozotocin treatment." (PMID 31743040, 2020). "There was a greater impact of maternal obesity than total GWG or diabetes on the increase in skinfolds thickness (+1.63 vs. 0.08 and 0.91 mm, respectively) and cord leptin (+2.88 vs. 0.12 and 0.85 ng/mL, respectively)." (PMID 33182482, 2020). "Leptin resistance in obese or type 2 diabetes mellitus (T2DM) patients is defined as a decrease in tissue response to leptin." (PMID 32655492, 2020). "High-fat and high-fructose diets have been used to induce animal model diabetes mellitus to evaluate the effect on change of leptin level." (PMID 31935815, 2020). "When evaluating predictors for cFT, we observed a similar pattern, where leptin, age, waist circumference, hypertension, and diabetes negatively predicted cFT levels (p < 0.05); E2 positively predicted cFT levels (R2 = 0.16, p = 0.0006)." (PMID 33179018, 2020). "High levels of leptin in the HFD mice and increased plasma glucose, insulin and IGF-1 in the serum indicated leptin resistance and insulin resistance, suggesting the onset of diabetes." (PMID 32639947, 2020). "Taken together, glycaemia, insulin and leptin are key mechanistic components of the diabetes–atherosclerosis axis." (PMID 32816039, 2020). "Adipokine markers such as Adiponectin, Chemerin and Leptin have previously been investigated in people with diabetes mellitus (DM) as well as women with GDM." (PMID 33206702, 2020). "LepRb is implicated in energy homeostasis; in this sense, the db/db mice (which lack LepRb) have an obese phenotype, with diabetes, pubertal disorders and elevated leptin levels." (PMID 32839413, 2020).
diabetes (continued). "A recent meta‐analysis has shown that aerobic exercise increases adiponectin and reduces leptin levels in adults with prediabetes and diabetes (Becic, Studenik, & Hoffmann, 2018)." (PMID 32652863, 2020). "This study assessed depression symptoms and biochemical indicators(levels of ghrelin, leptin, cortisol, and C-peptide levels) in type 2 diabetes mellitus (T2DM)." (PMID 33023555, 2020). "Covariates in the final MBDA-based CVD risk score were age, diabetes, hypertension, tobacco use, history of CVD (excluding MI/stroke), MBDA score, leptin, MMP-3 and TNF-R1." (PMID 33276814, 2020). "Compared with the remaining patients, the aortic stiffness group had high prevalence of diabetes mellitus, older age, higher waist circumference, body fat mass, systolic blood pressure, fasting glucose, and higher serum leptin level." (PMID 32403968, 2020). "It is thought that leptin contributes to autonomic dysfunction and cardiovascular risks in type 1 and type 2 diabetes mellitus (T1DM and T2DM)." (PMID 33076921, 2020). "Comparison of adiponectin/leptin and adiponectin/resistin ratios in newly diagnosed diabetes between normal BMI and obese subgroups." (PMID 32028423, 2020). "We aim to evaluate the effect of treating vitamin D deficiency or insufficiency on serum adiponectin, leptin, and leptin to adiponectin ratio (LAR) of type 2 diabetes mellitus patients." (PMID 33680012, 2020). "It was reported that either orexigenic neuropeptide galanin or anorexigenic hormone leptin caught benefit insulin sensitivity through increasing the translocation of glucose transporter 4 (GLUT4) in patients with diabetes." (PMID 32395890, 2020). "As a key regulator of energy balance, leptin, the other important enriched pathway has been reported to be a helpful gene in AD and diabetes." (PMID 33585009, 2020). "Leptin, adiponectin and resistin levels in the blood serum of patients with chronic pancreatitis and type 2 diabetes mellitus, M±m." (PMID 33456608, 2020). "The clinical course of chronic pancreatitis and type 2 diabetes mellitus is characterized by an imbalance in the regulatory function of adipokines, leptin, resistin and adiponectin." (PMID 33456608, 2020). "Standard of care for lipodystrophy includes treatment with leptin replacement if indicated, aggressive treatment of comorbidities such as diabetes and dyslipidemia, and genetic screening of relatives, if warranted." (PMID 29704234, 2019). "Analysis of the diabetes panel to determine if the TPM treatment had an effect on metabolic hormones revealed that HF feeding caused an increase in GIP, leptin, and insulin levels and a decrease in ghrelin; consistent with the literature." (PMID 30616618, 2019). "Leptin, a critical mediator of feeding, metabolism and diabetes, is expressed on an incidental basis according to satiety." (PMID 31661517, 2019). "Low leptin expression was observed in diabetes group as control group, whereas intensive leptin expression was observed in mirtazapine-applied diabetes goup especially near vena centralis." (PMID 31231496, 2019). "Obese, as compared to overweight patients, presented higher values of leptin and % of small HDL and lower large HDL; after statistical adjustment for diabetes, only the differences for leptin remained significant." (PMID 30911344, 2019). "In conclusion, multiple mouse models can be used to study diabetes-accelerated atherosclerosis, but the interpretation of the data has to be cautious given the various functions of leptin in many physiological processes." (PMID 31032262, 2019). "White adipose is also an endocrine organ that produces many adipokines (e.g., adiponectin, leptin and resistin), which are involved in diabetes and cardiovascular disease." (PMID 31665829, 2019). "The monogenic models are seminal for unveiling the intricate networks governing leptin and its receptors, and their involvement in diabetes mellitus." (PMID 31554925, 2019).
diabetes (continued). "Adiponectin and leptin are the most commonly used biomarkers in clinical practice and are also used in diabetes screening." (PMID 31379415, 2019). "This characteristic of leptin impairs glucose tolerance and hastens the onset of diabetes in obese individuals." (PMID 31488172, 2019). "When we observed leptin expressions by western blot, we saw that leptin expression decreased 1.14 fold in diabetes group and increased 1.29 fold in mirtazapine-administered diabetes group compared to control group." (PMID 31231496, 2019). "It has already been shown that circulating leptin concentration was significantly higher in women with heart failure or diabetes than men." (PMID 29867443, 2018). "The results of this study demonstrate that multiple markers including insulin, leptin/adiponectin, and 10- and 12-Z,E-HODE/LA can be used to detect diabetes risk at an early stage." (PMID 29610560, 2018). "The protein tyrosine phosphatase PTP1B, which is a negative regulator of insulin and leptin signaling, is a highly validated target for therapeutic intervention in diabetes and obesity." (PMID 29348454, 2018). "At age 7, she had diabetes, hypertriglyceridemia, low leptin levels and low body fat on dual energy X-ray absorptiometry (DEXA) scan, and was diagnosed with acquired generalized lipodystrophy (AGL)." (PMID 29610677, 2018). "Capsicum has been shown to help improve metabolism and hormone function, diabetes, and reduce insulin and leptin resistance." (PMID 30123516, 2018). "Recently, numerous investigations have suggested that leptin plays a critical role in the pathophysiology of diseases such as diabetes 50, lipodystrophy 51 and cardiovascular disease." (PMID 29372627, 2018). "In previous studies, the association between high-fat diet and arsenic in the incidence of diabetes was found, but the role of beta cells activity, liver mitochondrial oxidative stress, and hepatic enzymes (leptin, adiponectin and beta amylase) was unclear." (PMID 29755549, 2018). "After RYGB, leptin (protein and mRNA) decreased in patients with diabetes mellitus and dyslipidemia." (PMID 29849871, 2018). "Induction of diabetes decreased the level of insulin, leptin and high density lipoprotein (HDL) and increased the level of other lipids, glucose, and hepatic enzymes significantly (p<0.05)." (PMID 28348972, 2017). "In this paper it has also been demonstrated that the leptin concentrations in the blood of women with diabetes were significantly higher than in men." (PMID 28758947, 2017). "Leptin is an adipokines involved in the pathogenesis of obesity, insulin resistance, inflammation, and diabetes." (PMID 28078101, 2017). "Obese women with diabetes gained less weight during pregnancy and had lower serum leptin concentrations at delivery (p<0.05 for both criteria)." (PMID 28750045, 2017). "As expected, MetS patients had higher BMI values, %BF, cholesterol, HOMA-IR, serum free leptin and a higher prevalence of diabetes." (PMID 28719612, 2017). "Analysis of individual components of CHA2DS2-VASc score showed that hypertension, female gender, and diabetes had greatest impact on elevated serum leptin level." (PMID 29225622, 2017). "Administration of either leptin or insulin to the CNS in rats with streptozotocin-induced diabetes blocks this compensatory hyperphagia almost completely." (PMID 28303116, 2017). "The aim of this study is to investigate the effect of maternal diabetes on adipocytokines (adiponectin, leptin and TNF-α) production in F1 offspring in rats." (PMID 28078101, 2017). "As such, although leptin can also have effects on bone independently of diabetes, the db/db mouse represents a good model of T2DM, and reproduces the bone phenotype observed in most T2DM." (PMID 29209277, 2017).
diabetes (continued). "We assessed the possible effect of a commercially available bee honey (given orally by gavage at doses of 1 g/kg/day for 4 weeks) on the blood concentrations of glucose, insulin and leptin and body weight of rats with streptozotocin-induced diabetes." (PMID 28127544, 2017). "The absolute level of plasma leptin after the Palaeolithic diet was lower than after the diabetes diet (large effect size, Cohen’s d = −1.26; p = 0.023)." (PMID 27216013, 2016). "Leptin was recently shown to normalize glucose levels in a number of rat models of diabetes (summarized in Greenhill, 2014)." (PMID 26959237, 2016). "In our studies, in health we observe some physiologic correlations such as leptin and CRP, but in diseases with sustained inflammation such as RA or diabetes mellitus, we observe loss of some physiologic and emergence of pathologic correlations." (PMID 27981248, 2016). "The Palaeolithic diet resulted in a large effect size (Cohen’s d = −1.26) at lowering fasting plasma leptin levels compared to the diabetes diet [mean difference (95 % CI), −2.3 (−5.1 to 0.4) ng/ml, p = 0.023]." (PMID 27216013, 2016). "This study aimed to investigate the alteration of Neuropeptide Y (NPY) in the hypothalamus and its correlation with insulin, leptin and ghrelin during the development of a rat model of type 2 diabetes mellitus." (PMID 27867820, 2016). "Compared with IS individuals, all IR (IR + type 2 diabetes mellitus) individuals exhibited a significant reduction in plasma leptin and adiponectin, but had increased IL-6 levels." (PMID 27342408, 2016). "The adipokine leptin has been recently considered as a hormone candidate for managing diabetes in the absence or presence of insulin diabetes therapy." (PMID 27055280, 2016). "During the development of the type 2 diabetes mellitus rat model, both the fasting serum levels of insulin and leptin (ng/ml) elevated significantly and the fasting plasma ghrelin concentration decreased the hypothalamic NPY (pg/mg) content significantly." (PMID 27867820, 2016). "We previously reported the lost correlation between CRP and leptin in patients with type 2 diabetes mellitus, in which inflammation is considered to be a cornerstone of the disease." (PMID 27981248, 2016). "This positive association of serum adiponectin, leptin and LAR with CKD was consistently present in subgroups of gender, ethnicity, diabetes, hypertension and overweight status (all P-interaction >0.1)." (PMID 25793395, 2015). "This study examined the possible mediating effects of adiponectin, leptin, and C-reactive protein (CRP) concentrations on the smoking-diabetes association." (PMID 25400076, 2015). "Since leptin can influence diabetes, we have measured the level of this mediator in serum of starved mice of both strains." (PMID 26090474, 2015). "In STZ-diabetes induced mice, Zinc supplementation has shown to increase the serum leptin concentration." (PMID 26381880, 2015). "Cord blood leptin at term is increased by maternal diabetes independently of neonatal adiposity and is directly related to maternal hemoglobin A1c percent in offspring of diabetic and non-diabetic women." (PMID 26111704, 2015). "Among the agents, only use of insulin was independently associated with SDNN (β = −0.224, p = 0.034) together with plasma leptin (β = −0.256, p = 0.042) and duration of diabetes (β = −0.223, p = 0.041)." (PMID 26338087, 2015). "Leptin levels were found to be either same or lower in subjects with diabetes but significantly higher in obese and obese diabetic condition." (PMID 25897417, 2015). "The present study clearly shows that multiple markers, including 10- and 12-(Z,E)-HODE/LA, insulin, and leptin/adiponectin, can be used for the early detection of diabetes." (PMID 26132231, 2015).
diabetes (continued). "Leptin, insulin, and percentage of diabetes were similarly lowest in Ghanaians (26.5 ± 21.0 μg/L, 100.1 ± 44.3 pmol/L, and 1 %, respectively) and highest in the US (41.4 ± 19.2 μg/L, 170.0 ± 83.2 pmol/L, and 13 %, respectively)." (PMID 26374293, 2015). "Elevated serum and vitreous leptin was observed in patients with diabetes, and vitreous leptin was especially elevated in patients with PDR." (PMID 26605370, 2015). "Trans-eQTL were also more common than local eQTL in a previous miRNA eQTL mapping study involving an F2-intercross with diabetes resistant and susceptible strains (C57BL/6J and BTBR, respectively, each containing two mutant alleles of the leptin gene)." (PMID 26303911, 2015). "We aim to study the relationship between aging and chemerin, adiponectin, and leptin levels in type 2 diabetes mellitus (T2DM)." (PMID 25105135, 2014). "Plasma levels of adiponectin and leptin in healthy individuals or diabetes mellitus patients have been previously reported." (PMID 24528653, 2014). "The ob/ob and db/db mutations have been crossed onto atherosclerosis-prone strains of mice, but even in these models it is difficult to eliminate the confounding effects of leptin-related dyslipidemia from those of diabetes." (PMID 24809394, 2014). "Apart from the diabetes, leptin also affects a variety of other physiological functions, including fertility, bone metabolism, and immune responses." (PMID 23634778, 2013). "Major periodontal risk factors were recorded (age, gender, diabetes and smoking status), as well as plasma levels of inflammatory markers (CRP, orosomucoid, IL-6) and adipokines (adiponectin, leptin)." (PMID 23526947, 2013). "Reports regarding the role of leptin in diabetes are inconsistent; some studies have reported increased or decreased or unchanged serum leptin levels in diabetic patients." (PMID 23853613, 2013). "Results from obese Sudanese patients suggest that HOMA-IR and -β cell function are related to leptin in diabetes." (PMID 23853613, 2013). "In rodents with diabetes, leptin treatment normalized plasma glucose and increased insulin sensitivity." (PMID 23781317, 2013). "It was shown that subcutaneous fat produces more leptin compared to omental fat and that diabetics own more visceral and less subcutaneous fat; these considerations were not determined in current study." (PMID 23853613, 2013). "Appropriate exercise can effectively reduce serum leptin of diabetic rats and humans, ease leptin resistance, and inhibit the development of diabetes." (PMID 24455748, 2013). "These adipokines including leptin, visfatin, resistin, apelin, vaspin, and retinol binding protein-4 can regulate inflammatory responses and contribute to the pathogenesis of diabetes." (PMID 23772224, 2013). "This adipokine has known actions which protect against the development diabetes, but its levels are markedly increased in obese subjects, presumably in part to compensate for the state of leptin resistance." (PMID 23806173, 2013). "In uncontrolled diabetes, icv administration of leptin activates BAT, which leads to normalize blood glucose levels in STZ-induced diabetic rats." (PMID 23579596, 2013). "Several mutual proinflammatory cytokines and adipocytokines also act on the pathogenesis of autonomic neuropathy and diabetes, such as interleukin 6, C-reactive protein, leptin and adiponectin." (PMID 23424665, 2013). "There is some evidence supporting the effects of leptin on the cardiovascular system and Type 2 diabetes mellitus (T2DM)." (PMID 23216709, 2012). "Our study suggests that autonomic dysfunction is seen early in the course of diabetes, and that this occurs alongside alterations in various adipokines, including adiponectin and leptin, and various inflammatory adipocytokines, including IL-6." (PMID 22110481, 2012). "Placental leptin production is increased during hypoxia and in various obstetrical conditions such as diabetes, preeclampsia, and intrauterine growth retardation." (PMID 20940111, 2011).